PRL (prolactin)
Diseases named in the same sentence as PRL in open-access papers (continued):
Sharing a sentence is not in itself a finding about the gene and the disease.
endometriosis (continued). "The studies that suggested a relationshipbetween endometriosis and abnormal prolactin secretion are limited in number, andtheir results are controversial." (PMID 30969738, 2019). "Prolactin was found to have diagnosticvalue to detect endometriosis stages III/IV vs. stages I/II in AUC=0.65, 95%CI (0.55, 0.76)." (PMID 30969738, 2019). "Prolactin values with a cut off set at 20.08 ng/mL had asensitivity of 0.61 and specificity of 0.60 to detect endometriosis stages III/IVvs." (PMID 30969738, 2019). "Eleng capsules are also able to significantly relieve the symptoms and signs of endometriosis and blood stasis syndrome, potentially by down-regulating serum levels of prolactin (PRL), CA125, and anti-endometrial antibody (EMab)." (PMID 30402122, 2018). "The mean PRL level in the endometriosis group was (23.02±1.25 ng/mL) while in the controls was (17.21±1.22 ng/mL)." (PMID 26000006, 2015). "PRL levels were significantly higher in endometriosis group compared to control group (23.02±1.25 vs. 17.22±1.22 respectively, p=0.004)." (PMID 26000006, 2015). "Notably, PRMT5 overexpression restores IGFBP1 and PRL expression in eutopic ESCs of endometriosis patients, suggesting that PRMT5 dysregulation contributes to impaired decidualization in endometriosis." (PMID 40072055, 2025). "Additionally, dysregulation of the HPA axis contributes to elevated serum cortisol and prolactin levels in patients with endometriosis." (PMID 40130159, 2025). "The authors of a recent study proposed a panel of inflammatory markers, particularly IL-6, PRL, and CA 125, as a useful tool to identify women with advanced endometriosis who could qualify for treatment." (PMID 39407928, 2024). "Moreover, the PRL response to the LHRH/TRH test was exaggerated in patients with endometriosis compared to the normal controls." (PMID 39407928, 2024). "There is a possibility that increased prolactin serum levels in women with endometriosis could promote pelvic pain in these patients by dysregulating prolactin receptor expression." (PMID 39407928, 2024). "The essential question is what is the primary cause, and what is the consequence: hyperpolactinaemia that potentiates the development of endometriosis or enough endometriotic tissue that increases prolactin whether on a local or systemic level." (PMID 39407928, 2024). "Finally, overexpression of PRMT5 rescued the defective expression of IGFBP1 and prolactin in primary endometrial stromal cells from endometriosis patients." (PMID 36195592, 2022). "It has been suggested that prolactin may be involved in the pathogenesis of benign uterine diseases, including adenomyosis and endometriosis." (PMID 35956024, 2022). "The mechanism by which breastfeeding may have a protective impact on women with endometriosis involves the effect of prolactin (PRL) on the hypothalamic–pituitary axis." (PMID 34682348, 2021). "Significant differences were also observed in the concentrations of IL-6, hs-CRP and PRL when the non-endometriosis group (median values: 1.93 pg/mL, 0.99 mg/L and 22.78 ng/mL, respectively) was compared with the group of healthy women (p = 0.010, p = 0.037 and p < 0.001, respectively)." (PMID 33669013, 2021). "Serum concentrations of IL-1β, IL-6, hs-CRP, IgG, YKL 40 and PRL, in comparison to the well-known CA 125 levels, were studied with the aim of identifying an additional noninvasive inflammatory marker or set of markers characteristic for endometriosis." (PMID 33669013, 2021). "Such analysis determines whether the set of concentration values of CA 125, IL-6 and PRL can be used to differentiate serum samples in a way that reflects clinical characteristics typical for endometriosis." (PMID 33669013, 2021). "The proposed panel of inflammatory markers, especially IL-6, PRL and CA 125, may become a useful tool to identify women with advanced endometriosis who could qualify for treatment." (PMID 33669013, 2021).
endometriosis (continued). "Given the known capability of endometrium to secrete PRL during the normal luteal phase, a direct PRL secretion from endometriosis implants has been hypothesized." (PMID 33162942, 2020). "In addition, IGFBP-1 and PRL also show a lower secretion by cultured endometrial stromal cells from women with endometriosis than those from healthy women." (PMID 32063886, 2019). "In addition, far too little attention has beengiven to studies comparing prolactin levels in various stages of endometriosis." (PMID 30969738, 2019). "The relation between excessive prolactin and endometriosis-relatedinfertility is debatable." (PMID 30969738, 2019). "However; further studies of basal PRL concentrations in various stages of endometriosis are needed to confirm this relationship." (PMID 26000006, 2015). "A statistically significant relationship was found between the basal serum PRL level and the stage of endometriosis (16.98±1.29 ng/mL for stages I; 18.07±1.50 ng/mL for stages II; 25.59±1.96 ng/ mL for high stages III-IV) compared to healthy controls (17.21±1.22 ng/mL) (p=0.01)." (PMID 26000006, 2015). "Additionally, the protein levels of IGFBP1 and PRL were reduced following transfection with mPRβ siRNA, confirming that mPRβ is essential for the decidualization process in cells from healthy women and women with endometriosis." (PMID 40806428, 2025). "Since this early report, studies have sought to identify the relationship between prolactin serum levels and endometriosis as well as the validity of serum prolactin levels in diagnosing endometriosis and whether there are differences in the prolactin serum levels regarding stage of the disease." (PMID 39407928, 2024). "In ESCs isolated from both endometriosis patients and controls, P4 treatment (14 days) upregulates IGFBP1 and PRL expression." (PMID 40072055, 2025). "We next analyzed the expression levels of SOX4, PGR, FOXO1, HERC4, IGFBP1, and PRL in the mid-secretory endometrium of healthy women (control, n = 12) versus women who suffered RIF due to endometriosis (EMS-RIF, n = 12)." (PMID 35244538, 2022). "Primary hEnSCs isolated from the endometrial tissues of endometriosis patients showed impaired decidualization after differentiation stimulus, as revealed by IGFBP1 mRNA expression and secreted PRL levels." (PMID 36195592, 2022). "Particularly we avoided including anovulation or endometriosis because these diseases possibly interfere with ovarian reserve or HPO axis and, in turn, affect the PRL status." (PMID 32982975, 2020). "During endometriosis where increase activity of this pathway is present, a decrease in the decidual marker (IGFBP1 and PRL) was observed." (PMID 28475617, 2017). "Both Org OD 02-0 concentrations mimicked the effects of P4 by upregulating the expression of IGFBP1, PRL, HAND2, and ZBTB16 in control, eutopic, and ectopic cells from women with endometriosis, suggesting the involvement of mPRs in the decidualization process of endometrial cells." (PMID 40806428, 2025). "Most of the studies that measured the basal prolactin serum levels in patients with and without endometriosis reported higher basal prolactin serum levels in patients with endometriosis compared to healthy controls." (PMID 39407928, 2024). "It seems that danazol treatment of endometriosis does not lower the basal prolactin level as well as the response to the TRH and insulin challenge tests." (PMID 39407928, 2024). "Following TRH administration, a significant increase in prolactin serum concentration was observed in patients with endometriosis, suggesting that some patients with endometriosis exhibit a greater capacity for prolactin secretion than normal women." (PMID 39407928, 2024). "PRL values with a cutoff set at 17.5 ng/mL, which had a sensitivity of 0.64 and specificity of 0.63 in segregating subjects with and without endometriosis." (PMID 39407928, 2024).
endometriosis (continued). "Prolactin levels are significantly higher in women with endometriosis when compared to those of women without endometriosis." (PMID 36387918, 2022). "Elevated prolactin levels were also detected in women with endometriosis,irrespective of the stage of the disease." (PMID 36350241, 2022). "Aside from neoplastic diseases, PRL is thought to be involved also in the pathogenesis of endometriosis, which reportedly exerts a dramatic negative influence on woman fertility." (PMID 33162942, 2020). "Infertile women with more advanced endometriosis have higher prolactin levels thaninfertile women without endometriosis." (PMID 30969738, 2019). "In the patients suffering from both endometriosis and CE, the concentration of PRL tended to be decreased compared with the patients with endometriosis without CE (P = 0.09)." (PMID 28259137, 2017). "When only the samples with endometriosis were evaluated in the CE group (five patients) and the non-CE group (four patients), the mRNA levels of PRL and IGFBP-1 tended to be decreased in the CE group (P = 0.06 in both)." (PMID 28259137, 2017). "The results of some other studies on prolactin’s role in the development of endometriosis do not support the hypothesis that prolactin is involved in the formation of endometriosis." (PMID 39407928, 2024). "However, PRMT5 supplementation obviously promoted IGFBP1 mRNA expression (31.56 vs. 91.18, P < 0.05) and secreted PRL levels (85.17 vs. 115.33 ng/mL, P < 0.001), indicating that PRMT5 rescued the decidualization defect of endometrial stromal cells from endometriosis patients." (PMID 36195592, 2022). "In this study, significantly higher concentrations of serum prolactin were observed in the endometriosis (p < 0.001) and non-endometriosis groups (p < 0.001), in comparison to the healthy women from the control group (median values: 21.88 ng/mL, 22.78 ng/mL and 12.08 ng/mL, respectively)." (PMID 33669013, 2021). "A PRL level of greater than 17.5 ng/ml has been found to significantly discriminate patients with and without endometriosis, whereas a PRL level of greater than 20.08 ng/ml has been reported to significantly discriminate between mild (stage I-II) and severe (III-IV) endometriosis." (PMID 33162942, 2020). "This retrospective cohort study carried out at the Babol Infertility ResearchCenter looked into the baseline serum prolactin levels of 114 infertilewomen with endometriosis and compared them to the levels seen in 101infertile women without endometriosis (controls)." (PMID 30969738, 2019). "HDAC3 silencing in ESCs from women without endometriosis impairs in vitro decidualization, evidenced by decreased IGFBP1 and PRL expression." (PMID 40072055, 2025). "Additionally, we found that overactivation of the prolactin signaling pathway and the natriuretic peptide receptor 2 (NPR2) signaling pathway may promote the proliferation and migration of endometriotic cells, thereby exacerbating the condition of endometriosis." (PMID 40140093, 2025). "One study investigating the effect of 6 months of danazol treatment found the absence of a significant difference in the basal prolactin levels as well as in the response to the TRH and insulin challenge tests between the controls and patients with endometriosis, before and after danazol treatment." (PMID 39407928, 2024). "Our data shown that the significantly reduced protein level and mRNA expression of PRL and IGFBP-1 and the increase of cell number were oppositely observed in the CE patients compared with non-CE patients, no matter whether the patients have endometriosis or not." (PMID 28259137, 2017).
colorectal cancer (30 papers, 1990 to 2026). A primary or metastatic malignant neoplasm that affects the colon or rectum. "Circulating PRL can be higher in patients with colorectal cancer compared to controls and occasionally above the reference range and PRL has been proposed as a prognostic factor in colorectal cancer due to its possible association with a more unfavorable prognosis." (PMID 40478803, 2025). "First, the effect of TRAIL treatment on colorectal cancer cells that had been previously exposed to pregnancy levels of PRL was evaluated under static and shear conditions." (PMID 41501898, 2026). "When colorectal cancer cells that had previously been exposed to pregnancy levels of prolactin were treated with the dual affinity liposomes in whole blood under physiologically relevant shear stress, there was a significant decrease in cell viability." (PMID 41501898, 2026). "Further research is required to better understand the role of prolactin as a potential prognostic factor in colorectal cancer and to establish the relationship between serum prolactin and CEA." (PMID 40201873, 2025). "Results showed that for the target genes of the 29 candidate exo-miRNAs, KEGG pathways were mainly involved in pathways in cancer, renal cell carcinoma, prolactin signaling pathway, ErbB signaling pathway, and colorectal cancer." (PMID 38180107, 2023). "KEGG analysis revealed that the top 5 pathways identified were central carbon metabolism in cancer, mitophagy, prolactin signaling pathway, colorectal cancer, and thyroid hormone signaling pathway." (PMID 38180107, 2023). "We also noted a common increase in the hormone prolactin, which is commonly overexpressed in patients with colorectal cancer." (PMID 34611474, 2021). "To address this issue, we focused our research on the effect of PtGs and studied, in addition to FSH, the effects of luteinizing hormone (LH) and prolactin (PRL) on colorectal cancer (CRC) cell lines." (PMID 29494614, 2018). "Considering the fact that laboratory cost for detecting CEA is higher than PRL, We suggest PRL as a valuable tumour marker in colorectal cancer." (PMID 15617576, 2004). "Mean PRL serum level in colorectal cancer group was 21.6 ± 8.1versus 10.5 ± 4.6 in control group, which was significantly different (p < 0.0001)." (PMID 15617576, 2004). "High levels of locally synthesized PRL have been demonstrated in colorectal cancer." (PMID 40478803, 2025). "Elevated levels of prolactin have also been observed in various cancers, including CRC; however, the role of elevated prolactin in colorectal cancer remains unclear." (PMID 40201873, 2025). "This study demonstrates that PRL, a pituitary gland hormone, is elevated in colorectal cancer." (PMID 15617576, 2004). "However, elevated prolactin plasma levels in colorectal cancer patients remained unclear." (PMID 15617576, 2004). "The gene sets were also a part of pathways related to colorectal cancer, choline metabolism in cancer, HTLV-1 infection, TNF (tumor necrosis factor) signaling factor, and prolactin signaling pathway." (PMID 35039759, 2022). "Such PEA immunoassay has been applied for multiplex analysis of patients with colorectal cancer, which determined the significant correlation of the expression of CEA, IL-8, and prolactin with specific colorectal cancer stage." (PMID 33195320, 2020). "In the present study we found that serum PRL and CEA levels are increased in patients with colorectal cancer but the greater portion of the patients had an increased level of PRL compared with elevated level of CEA." (PMID 15617576, 2004). "The circulating preoperative median PRL and CEA levels were significantly higher in colorectal cancer patients than in their respective controls." (PMID 1419646, 1992). "The expression of PRL receptors and locally synthesized PRL has been reported in some cases of colorectal cancer, while other studies could not confirm these findings." (PMID 40478803, 2025).
migraine (29 papers, 2011 to 2025). "Prolactin enhances neuronal excitability and increases susceptibility to migraine triggers—particularly in females—via actions on trigeminal sensory neurons." (PMID 41052788, 2025). "Prolactin, which is under tonic inhibition by hypothalamic dopamine, has been implicated in migraine pathophysiology through its modulatory effects on trigeminal pain processing." (PMID 41052788, 2025). "Collectively, these findings support a prolactin‐dependent mechanism that increases migraine susceptibility." (PMID 41052788, 2025). "Reports show a direct correlation between high prolactin levels and the prevalence of chronic migraine, with increased risk of migraines in patients with hyperprolactinemia." (PMID 39439003, 2024). "Prolactin is a neurohormone that circulates at higher levels in females and that has been implicated clinically in migraine." (PMID 38658853, 2024). "Alterations in PRL have been observed in migraine patients, being associated with the progression of migraine." (PMID 38397400, 2024). "Regarding the relationship between PRL signalling and migraine (or prolactinoma- and/or pituitary diseases-associated headaches), clinical and preclinical studies have suggested the involvement of PRL and PRLR in headache disorders." (PMID 36967387, 2023). "Several factors cause sex differences in migraine, one of which is sex hormones such as estrogen, progesterone, and prolactin." (PMID 37190874, 2023). "While elevated PRL levels have been observed in almost all migraine patients, this elevation is also associated with chronicity of migraine and worsening prognosis in migraine patients." (PMID 36967387, 2023). "Research on PRL revealed that this endocrine hormone is linked with migraine as well as many other types of pain." (PMID 36967387, 2023). "Serum elevated prolactin (PRL) levels were associated with a variety of pain conditions as migraine, burning, rheumatoid arthritis, and osteoarthritis." (PMID 27518164, 2016). "For instance, the use of amitriptyline and valproate (the latter nowadays less commonly utilized in women of childbearing age) for migraine prevention, or the association of metoclopramide for the control of acute migraine attacks, may alter prolactin levels." (PMID 39634775, 2024). "In humans, stress increases circulating prolactin, lowers sensory thresholds increasing the likelihood of pain attacks, is associated with painful menstruation (i.e., dysmenorrhea) and importantly, is the most common self-identified migraine trigger." (PMID 38658853, 2024). "Prolactin plays a critical role in the complex sex-specific mechanisms underlying migraine." (PMID 39439003, 2024). "PACAP-38, another inflammatory agent that may have an accent role in migraine pathogenesis, has been shown to cause increased PRL release in MO patients." (PMID 36967387, 2023). "Despite the potential for increased androgen-mediated neuroprotection and repressed menstrual-related hormonal fluctuations to reduce migraine susceptibility, the imbalance of hormonal signaling might still induce headache via elevated estrogen and prolactin." (PMID 37795389, 2023). "Some of the limitations of this study include the case‐control design, which could be a source of bias when interpreting the findings because a cause‐and‐effect relationship cannot be confirmed between migraine and prolactin." (PMID 37190874, 2023). "However, migraines are three times more common in women than in men, and sex steroids and prolactin are likely to be implicated in migraine pathophysiology." (PMID 36430285, 2022). "Collectively, the studies presented above support the existence of a link between migraine and prolactin, however, it remains to be exactly elucidated how elevated endogenous prolactin levels can cause migraine and why different responses are seen in episodic versus chronic migraine." (PMID 34737888, 2021).